KLK11 (kallikrein related peptidase 11)
Description:
Possible multifunctional protease. Efficiently cleaves 'bz-Phe-Arg-4-methylcoumaryl-7-amide', a kallikrein substrate, and weakly cleaves other substrates for kallikrein and trypsin. Cleaves synthetic peptides after arginine but not lysine residues.
Synonyms: PRSS20; TLSP; IEKD
Tractability: Antibody: UniProt places it where antibodies can reach, with high confidence; UniProt predicts a signal peptide or a membrane-spanning region; its Gene Ontology location is reachable by antibodies, with medium confidence. PROTAC: ubiquitination databases record sites on it.
Target class: Serine protease; Enzyme; Serine protease PA clan; Serine protease S1A subfamily; Protease
Gene: Protein-coding gene on chromosome 19 (51,022,216 to 51,028,039, reverse strand). Ensembl gene ENSG00000167757.
Subcellular location: Secreted (Isoform 1); Golgi apparatus (Isoform 2); Secreted
Gene Ontology:
Molecular function: serine-type endopeptidase activity; serine-type peptidase activity
Biological process: protein maturation; proteolysis
Cellular component: extracellular exosome; extracellular region; Golgi apparatus; secretory granule
Genetic constraint (gnomAD): Loss-of-function variants: 13 observed, 21.76 expected, observed/expected ratio (o/e) 0.6, 90% interval 0.39 to 0.95. The upper end of that interval is the gene's LOEUF score, 0.95, which puts it in group 4 of 6, group 1 being the genes least tolerant of losing a copy. Missense variants: 285 observed, 322.35 expected, observed/expected ratio (o/e) 0.88, 90% interval 0.8 to 0.98. Synonymous variants: 131 observed, 128.67 expected, observed/expected ratio (o/e) 1.02, 90% interval 0.88 to 1.18.
Homologues: Orthologues: chimpanzee KLK11 (98% identical), macaque KLK11 (92% identical), pig KLK11 (85% identical), dog KLK11 (82% identical), rat Klk11 (82% identical), mouse Klk11 (80% identical), rabbit KLK11 (80% identical), tropical clawed frog klk1 (46% identical), Drosophila melanogaster CG32808 (29% identical), Drosophila melanogaster Phae2 (27% identical), Drosophila melanogaster CG3916 (26% identical), Drosophila melanogaster Send2 (26% identical), and 7 more. Paralogues in human: KLK5 (49% identical), KLK12 (48% identical), KLK14 (48% identical), KLK8 (47% identical), KLK2 (44% identical), KLK1 (43% identical), KLK7 (42% identical), KLK3 (40% identical), KLK4 (39% identical), TMPRSS4 (32% identical), PRSS58 (28% identical), PRSS54 (20% identical).
Diseases named in the same sentence as KLK11 in open-access papers:
KLK11 is named in the same sentence as 65 diseases in open-access papers, as found by Europe PMC text mining. Sharing a sentence is not in itself a finding about the gene and the disease. The quoted sentences say what the papers report.
ovarian carcinoma (14 papers, 2014 to 2023). A malignant neoplasm originating from the surface ovarian epithelium. "The patients with high KLK11 expression were associated with shorter survival in metastatic colorectal cancer and ovarian cancer." (PMID 34067437, 2021). "For example, KLK15 expression is an independent marker of prognosis in ovarian cancer, KLK9 has been shown to be a marker for prognosis in breast and ovarian cancer, and increased KLK11 expression in gastric carcinoma is associated with poor prognosis." (PMID 29707153, 2018). "However, there are several studies on gastric, prostate, and ovarian cancer, which reported an association of high KLK11 expression in tumor tissue with a favorable patient prognosis." (PMID 36294951, 2022). "KLK11/hK11 was reported to be highly expressed in ovarian cancer patients, mostly early-stage tumours and is thus a potential marker of favourable prognosis." (PMID 35031764, 2022). "In a previous study, we have observed that the combination of the coordinately expressed proteases KLK10 and KLK11 leads to better accuracy in terms of prognostic biomarkers in ovarian cancer than either KLK10 or KLK11 alone." (PMID 33087135, 2020). "Based on KLK11 serum levels, it has been proposed that ovarian cancer cases can be distinguished from healthy controls, who display very low KLK11 expression." (PMID 29095848, 2017). "For validation of the results obtained for KLK11 mRNA, we analyzed publicly available Affymetrix-based mRNA data from ovarian cancer patients applying the biomarker assessment tool Kaplan-Meier Plotter." (PMID 29095848, 2017). "Recent studies have reported that KLK11 has been expressed in many cancers, including prostate cancer, ovarian cancer, gastric cancer, as well as rectal carcinoma." (PMID 24510347, 2014). "An immunofluorometric assay study demonstrated that KLK11 expression in ovarian cancer tissues is a marker of favorable prognosis, since patients with KLK-positive tumors exhibit a longer progression-free survival (PFS) and overall survival (OS)." (PMID 24510347, 2014). "Several other studies previously reported KLK11 as prognostic biomarker for ovarian cancer as well." (PMID 29095848, 2017). "Furthermore, our data strongly indicate co-expression of KLK10 and KLK11 on the mRNA level in advanced ovarian cancer, which has already been observed in non-small-cell lung and breast cancer." (PMID 29095848, 2017). "Among the KLK11-14, KLK13 expression was reported as a favorable prognostic marker in breast cancers and ovarian cancers which is consistent with our present results." (PMID 37176127, 2023). "In fact, in the present study, we found a positive coregulation of KLK10 and KLK11 in TNBC tissue, a mechanism that has also been described in other cancer entities, such as ovarian cancer." (PMID 36294951, 2022). "Another study showed that seven genes (KLK5-8, KLK10, KLK11, and KLK14) were elevated in ovarian cancer tissue samples and cell lines compared with the healthy ovary." (PMID 33150763, 2020). "Whereas in the normal ovary only KLK10 and to a lesser extent KLK11 and KLK14 are expressed, most of the members of the KLK family are considerably upregulated in ovarian cancer." (PMID 30811511, 2019). "Multivariable Cox regression analysis of clinical outcome in advanced ovarian cancer patients (FIGO III/IV) with respect to clinical parameters and KLK11/KLK15." (PMID 29095848, 2017). "High protein levels of KLK4–7 and KLK10 have been found in ovarian cancer tissues, while KLK5–8, KLK10, KLK11, KLK13 and KLK14 were found in ascites fluid from ovarian cancer patients as reviewed." (PMID 24043563, 2014). "The hierarchical clustering revealed a group of proteins that have previously been reported to be expressed at elevated levels in ovarian cancer serum samples, including: CA125 (MUC16), HE4, MSLN, MK, KLK8, KLK11, NECT4, FOLR1, as well as KLK13, KLK14, and IL6." (PMID 35804849, 2022).
ovarian carcinoma (continued). "High KLK11 but not the other KLK mRNA levels can be considered as strong independent favorable prognostic factor in this major ovarian cancer subtype." (PMID 29095848, 2017). "In addition to the negative impact of KLK10 and KLK11 expression in TNBC on patient prognosis, the contradictory data from other cancer entities, such as ovarian cancer, cannot yet be explained." (PMID 36294951, 2022).
asthma (7 papers, 2019 to 2025). "In the context of asthma and other inflammatory conditions, airway epithelial cells release factors such as CCL20, thymic stromal lymphopoietin (TLSP; also known as KLK11), IL-33, IL-25 and granulocyte-macrophage colony-stimulating factor (GM-CSF; also known as CSF2)." (PMID 39508347, 2024).
breast carcinoma (7 papers, 2015 to 2023). "KLK11 expression was inversely associated with tumor grade in breast carcinomas, although the association between KLK11 and prognosis has not been reported in breast cancers." (PMID 37176127, 2023). "KLK11 expression levels are higher in low-grade than in high-grade breast cancer tissues and even a loss of KLK11 was described in highly malignant tissues." (PMID 36294951, 2022). "In this study, KLK11-14 genes were predominantly expressed in low-grade malignancies of breast carcinomas." (PMID 37176127, 2023). "Still, KLK11 expression is highest in TNBC among all breast cancer subtypes and, as shown in the present study, high KLK11 expression levels in TNBC patients were associated with a poor patient prognosis." (PMID 36294951, 2022). "Upregulation of KLK11 expression in breast cancer tissue vs. adjacent healthy tissue was found to be associated with the presence of the estrogen receptor." (PMID 36294951, 2022). "The overall expression of KLK10 and KLK11 in TNBC in comparison to the other KLKs was assessed using the publicly available TCGA breast cancer dataset." (PMID 36294951, 2022). "In breast cancer, KLK11 was identified as a marker for early stages since its expression was diminished or even lost in the course of disease progression." (PMID 36294951, 2022). "KLK11 is thought to be a prostate, ovarian, and breast cancer biomarker." (PMID 38022651, 2023). "Additionally, KLK11 was identified as one of the estrogen-induced genes in MCF-7 breast cancer cells." (PMID 37176127, 2023). "Altogether, KLK10 and KLK11 may have the potential to serve as prognostic biomarkers, and represent possible targets for therapy in breast cancer." (PMID 36294951, 2022). "Although previous studies have demonstrated the crucial role of KLK10 and KLK11 in breast cancer patients’ relapse, disease progression and shorter survival rates, a potential role for the KLK gene family in lymph node metastasis was first proposed in the present study." (PMID 26311227, 2015). "We applied an absolute quantitative real-time RT-PCR to quantitate the expression of CK19, KLK11, and CLEC3A mRNAs in 79 FFPE SLNs from 35 breast cancer patients." (PMID 31983196, 2020). "In summary, although very limited study has been conducted on the expression levels of KLK11 and CLEC3A mRNAs in the SLN tissue in breast cancer, we observed the overexpression of these genes in the positive SLN tissue similar to the CK19 biomarker." (PMID 31983196, 2020). "Concerning KLK11, the prognostic impact in breast cancer is still not completely understood." (PMID 36294951, 2022). "In breast cancer cells, androgens were shown to synergistically enhance estrogen-dependent expression of KLK10 and KLK11 indicating that coordinate expression of KLK10 and KLK11 may rely on hormone-dependent regulatory mechanisms as well." (PMID 29095848, 2017).
prostate carcinoma (6 papers, 2007 to 2021). A carcinoma that arises from epithelial cells of the prostate gland. "Kallikrein 11 (KLK11) expression in prostate cancer has an inverse association with tumor aggressiveness." (PMID 33490732, 2021). "Numerous studies have investigated the use of serum levels of KLK11 as a diagnostic marker to discriminate between prostate cancer and BPH." (PMID 20027305, 2009). "Nasser et al68 showed that in patients with intermediate-risk prostate cancer treated with definitive EBRT, KLK11 levels increased significantly during RT." (PMID 33490732, 2021). "Meanwhile, elevated kallikrein-related peptidase 11 (KLK11) mRNA expressions have been found to be associated with a less advanced stage, lower Gleason score, and an optimistic disease course for prostate cancer." (PMID 24809052, 2014). "The serine protease KLK11 appears to be regulated in prostate cancer with negative correlation between aggressiveness and expression." (PMID 17430594, 2007).
colon cancer (4 papers, 2009 to 2022). "We showed that, although many KLKs transcripts are upregulated in colon cancer-derived cell lines, KLK6, KLK10, and KLK11 are the most highly secreted proteins." (PMID 35883559, 2022). "Nine KLKs (KLK5-8, KLK10, KLK11, KLK13-15) were measured using ELISA assays in cytosolic extracts of 122 colon cancer tissues and their nearby normal mucosa, obtained during surgery." (PMID 19367279, 2009).
colorectal cancer (4 papers, 2018 to 2021). A primary or metastatic malignant neoplasm that affects the colon or rectum. "The inhibition of KLK11 significantly suppressed tumor growth and induced apoptosis of colorectal cancer cells." (PMID 34067437, 2021). "In human colorectal cancer cells, KLK11 knockdown inhibited cell proliferation and increases oxaliplatin sensitivity." (PMID 34059001, 2021). "The same research group also knocked down KLK11 in colorectal cancer cell line and shown that decreasing of KLK11 expression inhibited the cell proliferation and enhanced the sensitivity to oxaliplatin." (PMID 30355311, 2018). "Similarly, the knockdown of KLK11 has been reported to enhance the apoptosis of colorectal cancer cells." (PMID 31060300, 2019). "Since the expression of either KLK11 or CCDC25 was associated with the metastasis of colorectal cancers, the expressions of CCDC25 and KLK11 in CCA with or without lymph node metastasis were analyzed." (PMID 34067437, 2021).
gastric cancer (3 papers, 2021 to 2023). A primary or metastatic malignant neoplasm involving the stomach. "In agreement with our results, higher levels of KLK11 expression in gastric carcinoma were associated with poor overall survival." (PMID 34067437, 2021). "Conversely, the expression of genes encoding for Ghrelin (GHRL) and Kallikrein Related Peptidase 11 (KLK11) was decreased in intestinal gastric cancer compared with diffuse histotype." (PMID 34012923, 2021). "For these reasons, our results suggest that FPR2, CARD14, CXCR2, EFNA2, CXCR1, AQP9 TRIP13, along with GHRL and KLK11, could be used as promising biomarkers for gastric cancer diagnosis or prognostic evaluation." (PMID 34012923, 2021).
lymph node metastasis (3 papers, 2015 to 2023). "KLK11 expression was associated with lymph node metastasis in low rectal carcinoma." (PMID 34067437, 2021). "The correlation between the CCDC25 and KLK11 expressions in the cancerous tissues of CCA with/without lymph node metastasis was analyzed using Spearman’s test." (PMID 34067437, 2021). "However, a significant correlation was observed between KLK11 and CCDC25 expressions in CCA with lymph node metastasis (p = 0.028 and r = 0.593), but not in CCA without lymph node metastasis (p = 0.417 and r = 0.600)." (PMID 34067437, 2021).
serous ovarian cancer (3 papers, 2017 to 2022). "Consistent with these earlier studies, we showed that most of the advanced high-grade serous ovarian cancer samples displayed robust expression of KLK10 and KLK11." (PMID 29095848, 2017). "In contrast to KLK9 and 10, in the present study, high KLK11 mRNA levels were found to be an independent favorable predictor for both OS and PFS in advanced high-grade serous ovarian cancer." (PMID 29095848, 2017). "In summary, whereas KLK9 and KLK10 mRNA expression does not display any prognostic power in advanced high-grade serous ovarian cancer (FIGO stage III/IV), high KLK15 and, especially, KLK11 mRNA levels are associated with better outcome." (PMID 29095848, 2017). "Therefore, it is not too surprising that we observed indication for coordinate expression of some KLKs such as KLK6/KLK8 (Spearman correlation of mRNA levels: rs = 0.636;), KLK10/KLK11 (rs = 0.647;), or KLK5/KLK7 (rs = 0.568; unpublished results) in advanced high-grade serous ovarian cancer." (PMID 30811511, 2019).
adenoma (2 papers, 2014 to 2016). A neoplasm arising from the epithelium. "The commonly increased genes in these two adenoma samples include KLK11, which is also mutated in 4 of 11 adenoma samples." (PMID 27100181, 2016).
cholangiocarcinoma (2 papers, 2021 to 2023). A carcinoma that arises from the intrahepatic biliary tree (intrahepatic cholangiocarcinoma) or from the junction, or adjacent to the junction, of the right and left hepatic ducts (hilar cholangiocarcinoma). "A Kaplan-Meier survival curve study demonstrated that elevated KLK11 expression was linked to a poor prognosis of cholangiocarcinoma." (PMID 38022651, 2023).
laryngeal carcinoma (2 papers, 2015 to 2023). Carcinoma that arises from the laryngeal epithelium. "According to one study, KLK11 mRNA expression is a unique and independent biomarker in laryngeal cancer that can be used for diagnostic and prognostic purposes." (PMID 38022651, 2023). "Both studies reported a remarkable down-regulation of either KLK4 or KLK11 transcript levels in laryngeal cancer as compared to their non-malignant counterparts." (PMID 25990935, 2015).
lung adenocarcinoma (2 papers, 2018 to 2022). A carcinoma that arises from the lung and is characterized by the presence of malignant glandular epithelial cells. "Lung adenocarcinoma and lung squamous cell carcinoma showed significant up-regulation of 3 KLKs: KLK6 (7-fold and 19-fold), KLK8 (3-fold and 15-fold) and KLK12 (2-fold and 3-fold) and significant down-regulation of KLK11 (6-fold and 5-fold)." (PMID 29707153, 2018).
rectal cancer (2 papers, 2021 to 2023). A primary or metastatic malignant neoplasm that affects the rectum. "Also, the patients with low KLK11 expression showed better survival rates than those with high expression in low rectal carcinoma." (PMID 34067437, 2021).
thyroid cancer (2 papers, 2018 to 2024). "In a recent study, KLK11 mRNA levels were reported to be overexpressed in thyroid cancer compared with adjacent normal thyroid tissues, while its silencing in PTC cell lines inhibited proliferation, migration and invasiveness." (PMID 39787026, 2024).
triple-negative breast carcinoma (2 papers, 2022 to 2023). An invasive breast carcinoma which is negative for expression of estrogen receptor (ER), progesterone receptor (PR), and human epidermal growth factor receptor 2 (HER2). "In the present study, we quantified mRNA expression levels of KLK10 and KLK11 in a well-defined cohort of patients afflicted with triple-negative breast cancer, and evaluated their potential as prognostic factors." (PMID 36294951, 2022).
breast invasive carcinoma (1 paper, 2018). "Five KLKs were commonly downregulated in head-neck squamous cell carcinoma and breast invasive carcinoma: KLK3 (3-fold and 4-fold), KLK6 (2-fold and 6-fold), KLK7 (2-fold and 10-fold), KLK11 (5-fold and 6-fold) and KLK13 (8-fold and 3-fold)." (PMID 29707153, 2018).